KDM3A (lysine demethylase 3A)
Diseases named in the same sentence as KDM3A in open-access papers (continued):
Sharing a sentence is not in itself a finding about the gene and the disease.
tumor (continued). "Mouse tumor tissues were subject to qRT-PCR and Western blot analysis, and the results demonstrated that the miR-202-3p agomir diminished the protein expression of KDM3A, HOXA1, and MEIS3 in nude mice." (PMID 33520978, 2020). "Conversely, KDM3A overexpression induces the formation of pancospheres in human non-cancerous pancreatic ductal cells and tumor formation and causes metastasis in mice." (PMID 32354028, 2020). "Therefore, Kdm3a can be either a cancer driver or a tumor suppressor, depending on the differential cellular environments of different tumor types." (PMID 29156681, 2017). "Accordingly, whether Kdm3a can be targeted for cancer treatment should be determined by its tumor-promoting or tumor-suppressing role in the specific cancer type." (PMID 29156681, 2017). "We also observed no impact on cell growth in the non-transformed breast epithelial cell line MCF-10A following KDM3A depletion, suggesting that compounds which affect KDM3A activity may be useful as tumour specific BCa therapies." (PMID 25488809, 2015). "In addition, combining anti‐PD1 therapy with KDM3A inhibition effectively inhibited tumor growth." (PMID 39031630, 2024). "Thus, KDM3A is an important regulator for tumor growth and metastasis." (PMID 33888871, 2022). "Thus, we performed a co-transfection assay to further explore whether YAP1 is also involved in miR-335-induced inhibition of tumor growth and metastasis, as is KDM3A." (PMID 33888871, 2022). "Furthermore, KDM3A has been reported to be involved in multiple biological activities in tumours." (PMID 34350711, 2021). "KDM3A's ability to regulate metabolic gene expression by controlling AR binding site availability in hypoxic cells may be the molecular action KDM3A utilizes to stimulate tumor progression." (PMID 28416760, 2017). "However, the presence of KDM3A could oppose the angiogenic role of G9a to inhibit angiogenesis and tumor growth." (PMID 29156681, 2017). "However, some studies also considered KDM3A as a possible tumor suppressor." (PMID 29156681, 2017). "We further examined whether KDM3A/B were required for CSC-mediated tumour formation in vivo." (PMID 28440295, 2017). "It promotes MM survival under hypoxia by regulating the HIF-1α-KDM3A axis, and interacts with the poly(A) polymerase FAM46C, a known tumor suppressor, enhancing cell migration and invasion." (PMID 41596492, 2026). "The gene expression analysis revealed that several hub genes, such as ETNK1, KDM3A, EZH2, SMARCA4, and CASP3, were significantly overexpressed in HCC tissues, suggesting their potential roles in tumor progression and as biomarkers for HCC." (PMID 40074445, 2025). "Specific methyltransferases such as EZH2, EHMT1/2, and KMT1A, and demethylases including KDM3A/B and KDM4B, form oncogenic axes that sustain tumor growth and block myogenesis." (PMID 40508013, 2025). "The KDM3A/KLF5/SMAD4/EGFR axis coordinates the regulatory mechanism involved in maintaining a low population of T cells within the tumor microenvironment (TME), thus driving resistance to immunotherapies." (PMID 39519018, 2024). "Further assessments of BGC823 cell‐derived xenografts in nude mice revealed that treatment with KDM3A inhibitors IOX1 and BIX01294 suppressed tumor growth, decreased tumor volume, and reduced tumor weight in vivo." (PMID 39031630, 2024). "Ablation of KDM3A, KLF5, SMAD4, or EGFR elevates the population of tumor-infiltrating T cells and dendritic cells and decreases myeloid cell infiltration." (PMID 39519018, 2024). "KDM3A deletion in gastrointestinal tumor cells resulted in enhanced antitumor immunity following anti‐PD1 treatment and reduced tumor size in syngeneic mice." (PMID 39031630, 2024). "The intersection set analysis of the bioinformatics database and transcriptome array data identified six common genes, FSTL1, GDF15, IQSEC2, KDM3A, LTC4S and TCTEX1D4, in which most of them were involved in tumor cell proliferation and growth." (PMID 38201443, 2023).
tumor (continued). "This leads to overexpression of the H3K9me1/2 histone demethylase KDM3A (JMJD1A/JHDM2A) and tumor growth." (PMID 36768203, 2023). "These genes were FSTL1, GDF15, IQSEC2, KDM3A, LTC4S and TCTEX1D4, in which most of them were involved in tumor cell proliferation and growth." (PMID 38201443, 2023). "JMJD1A (KDM3A) is overexpressed in BCa and it has been correlated with metabolic reprogramming, resulting in tumor progression." (PMID 37228649, 2023). "Lysine Demethylase 3A (KDM3A), Forkhead-Box (FOX), B-cell lymphoma (BCL), and Krüppel-like factor (KLF) are the other genes that are repressed by SALL4 leading to promotion of tumor progression in cancer cells." (PMID 36010677, 2022). "Together, our findings verified the functional correlation between miR-335 and YAP1, and identified a new miR-335/KDM3A/YAP1 regulatory axis, which plays an important role in tumor growth and metastasis in ccRCC." (PMID 33888871, 2022). "Taken together, the present study demonstrates that the histone modifier KDM3A epigenetically activates SP1 transcription, which further activates the glycolysis-related PFKFB4 in OS, consequently leading to tumor cell growth and metastasis." (PMID 35590288, 2022). "Our experiments have shown that the inhibitory role of miR-335 in cell proliferation, invasion, and migration relied on both KDM3A and YAP1, supporting the essential role of the miR-335/KDM3A/YAP1 axis in ccRCC tumor growth and metastasis." (PMID 33888871, 2022). "Knock-down of KDM3A, KLF5, SMAD4 or EGFR in tumour cells influenced the immune TME and re-sensitized tumours to combination immunotherapy." (PMID 33671588, 2021). "Hypoxia is a key feature of the tumor microenvironment and tumor infiltrated NK cells are enriched for hypoxia signatures, including expression of HK2, SLC7A5, SLC2A3, and KDM3A." (PMID 34177887, 2021). "RT‐qPCR and Western blot analyses were conducted to determine the expression of let‐7i, KDM3A, DCLK1 and FXYD3 in tumours." (PMID 33350586, 2021). "Collectively, the experimental data demonstrated that miR-202-3p harbored tumor-suppressive properties during the development and progression of HCC through the KDM3A/HOXA1/MEIS3 axis in vitro and in vivo." (PMID 33520978, 2020). "Next, we quantified the expression of miR-202-3p and KDM3A in 50 HCC tissues and 38 tumor-free liver tissues." (PMID 33520978, 2020). "Mechanistically, RNA-based therapeutics MALAT1 activates the EZH2/STAT3 axis, modulates the HIF-1α-KDM3A pathway under hypoxia, interacts with FAM46C to drive migration, and sponges tumor-suppressive miRNAs such as miR-125b, miR-1271-5p, miR-509-5p, miR-188-5p, and miR-15a/16." (PMID 41596492, 2026). "Demethylases (e.g., KDM3A/B, KDM4B) reverse these marks and promote tumor growth." (PMID 40508013, 2025). "While KDM6A and KDM6B have a tumor suppressor role, other members of the KDM family like KDM2B, KDM3A, and KDM5A may serve as oncogenes in PDAC." (PMID 38791111, 2024). "Overexpression of KDM2B and KDM5A genes plays significant roles in promoting poor differentiation and tumor proliferation in PDAC, respectively, whereas knockdown of the KDM3A gene leads to decreased invasive activities in culture and impedes the formation of orthotopic tumors in mice." (PMID 38791111, 2024). "Of note, Kdm3a is a histone demethylase to regulate the availability of chromatin, while Lrp5 is a co-receptor of Wnt signaling and MMP9 is a matrix metalloproteinase to promote tumor migration." (PMID 35547745, 2022). "We observed that histone demethylase, Kdm3a, was downregulated in tumor cells treated with Oct4 CM and c-Myc CM, but it was not altered by the treatment with Sox2 CM and Klf4 CM." (PMID 35547745, 2022). "Moreover, we found H3K9me1/2 histone demethylase KDM3A as a novel downstream target of miR-335, and identified a new miR-335/KDM3A/YAP1 regulatory axis, which appears to play important roles in ccRCC tumor growth and metastasis." (PMID 33888871, 2022).
tumor (continued). "Downregulation of KDM3A in HCT116 CRC cells inhibits the clonogenic activity of CRC cells, arrests cell cycle progression, suppresses CRC cell proliferation and migration, and reduces xenograft tumor formation." (PMID 32354028, 2020). "Notably, Kdm3a is highly expressed in Cd44 (a liver CSC marker)-positive hepatocytes, and it controls the number and tumor-initiating potential of Cd44-positive cells." (PMID 32354028, 2020). "The study of a co-regulatory mechanism between KDM3A and KDM4B in hypoxic signalling may therefore also be beneficial for the development of novel therapeutic strategies to abrogate hypoxia driven tumours." (PMID 31390833, 2019). "We found that KO of Kdm3a did not significantly change the tumorigenic latency, but it significantly slowed down the tumor growth rate." (PMID 29156681, 2017). "The lysine demethylase 3A (KDM3A, JMJD1A or JHDM2A) controls transcriptional networks in a variety of biological processes such as spermatogenesis, metabolism, stem cell activity, and tumor progression." (PMID 28416760, 2017). "Similarly, we found that the depletion of KDM3A/B in CSCs isolated from human CRC tissues of the patient in case 2 also inhibited tumorsphere formation in vitro and tumour formation in vivo by inhibiting Wnt/β-catenin signalling." (PMID 28440295, 2017). "KDM3A (lysine demethylase 3A; Gene ID: 55818; also referred to as JMJD1A or JHDM2A) is crucial for gene regulation in a variety of biological activities such as spermatogenesis, metabolism, stem cell activity and tumor progression by demethylating mono- or di-methylated H3K9." (PMID 28416760, 2017). "The analysis on clinicopathologic parameters of patients suggested that a high KDM3A level was correlated with large tumor size, lymph node metastasis, and increased AJCC/TNM stages, although the level was not correlated with the sex, age, and tumor location." (PMID 35590288, 2022).
cancer (77 papers, 2013 to 2025). A tumor composed of atypical neoplastic, often pleomorphic cells that invade other tissues. "Genetic ablation of KDM3A reduces the infiltration of cancer-associated fibroblasts, promotes T-cell infiltration, and sensitizes tumors to combination immunotherapy." (PMID 38535087, 2024). "Lysine demethylase 3A (KDM3A) is a specific demethylase for H3 lysine 9 dimethylation (H3K9me2) and has been implicated in cancer development and chemoresistance, making it a promising therapeutic target." (PMID 37305393, 2023). "KDM3A has been summarized to be aberrantly expressed and associated with cancer development through its potent regulation on gene expression by removing H3K9me1/me2." (PMID 35590288, 2022). "In this report, we only performed loss-of-function assays of KDM3A to examine its relevance to cancer cell development." (PMID 35590288, 2022). "It has been reported that KDM3A-mediated transactivation of ETS1 occurs via a decrease in H3K9me2 is linked to cancer metastasis." (PMID 35338235, 2022). "Among the four KDMs, this review focuses on the relatively well-studied association between KDM3A and various cancers." (PMID 32354028, 2020). "The cancer systems biology analysis expanded underlying transcription factor motifs associated with oncogenic KDM3A demethylation, suggesting an underlying transcriptional network that directs transcriptional activation." (PMID 28416760, 2017). "Loss-of-function mouse models of Kdm3a phenocopy features associated with human ciliopathies, whereas human somatic mutations correlate with poor cancer prognosis." (PMID 28246120, 2017). "In cancer, KDM3A is often overexpressed and associated with poor prognosis." (PMID 38003596, 2023). "Thus, through the logic of “guilt by association”, it is plausible that the role of KDM3A in cancer may extend to involving interactors of the newly identified substrates in this study." (PMID 35625569, 2022). "The epigenetic regulatory role of KDM3A in the Wnt/β-catenin signaling pathway has been established in cancer context." (PMID 40033066, 2025). "In our study, we have consistently observed that KDM3A is expressed in both the cytoplasm and nucleus of NSPCs and cancer cell lines." (PMID 40033066, 2025). "Although much is studied about the roles of KDM3A in cancers compared to those of KDM3B and KDM3C, the latter two lysine demethylases are not to be overlooked." (PMID 38926399, 2024). "The histone lysine demethylase 3 A (KDM3A) is vital for the regulation of cancer physiology and pathophysiology." (PMID 38165573, 2024). "While a predominant number of research reports on the significant role of KDM3A in various cancers, an increasing number of studies imply aberrant activities of KDM3B and KDM3C and their deregulation in a variety of cancers." (PMID 38926399, 2024). "KDM3A is a specific demethylase for H3K9me2 and has been shown to be induced by hypoxia, promoting cancer cell invasion and contributing to radio-resistance." (PMID 37305393, 2023). "Insights into their dynamics, such as the differential expression of CD44 and DCLK1 isoforms or the regulatory role of KDM3A, can provide potential therapeutic strategies for more effective cancer treatments." (PMID 38003596, 2023). "Given the significance of KDM3A in cancer, here, we applied this approach to study the substrate specificity of this JmjC KDM and thereby aid in future substrate discovery explorations." (PMID 35625569, 2022). "KDM3A is upregulated in several cancers and coordinates with multiple oncogenic transcription factors (e.g., c-Myc, androgen receptor, estrogen receptor, β-catenin, hypoxia-inducible factor-1α, etc.)to promote cancer progression and therapeutic resistance." (PMID 35625569, 2022). "Among the pathways, hsa05202 (Transcriptional misregulation in cancer) attracted our attention since KDM3A mainly functions as a transcriptional regulator in cancer." (PMID 35590288, 2022).
cancer (continued). "Recently, KDM3A (H3K9 demethylase) has been identified as a critical effector of anoikis in cancer cells." (PMID 35186918, 2022). "Both mRNA and protein levels of KDM3A were upregulated in cancer tissues, determined using qPCR, western blot, and IHC." (PMID 33888871, 2022). "In a former research focusing on NSCLC, the aberrantly elevated KDM3A expression manifests in cancer tissues and knocking down KDM3A attributes to the suppression on cell biological functions." (PMID 34044859, 2021). "Many histone demethylases have been proven to promote the genesis and development of cancer, such as KDM3A, KDM4A, KDM4D, and JMJD6." (PMID 34980950, 2021). "KDM3A has also been found to be increased in pancreatic tumors and promote cancer genesis by regulating expression of DCLK1." (PMID 34980950, 2021). "Several KDMs play an active role in metabolic rewiring in cancer, for example, KDM3A/JMJD1A, which promotes BC progression by enhancing glycolysis through the coactivation of HIF-1α." (PMID 34072826, 2021). "Taken together, these data highlight the common role of KDM3A in different cancers, further reinforcing its prominent role in tumorigenesis." (PMID 32354028, 2020). "Overall, these findings support the indispensable function of KDM3A in colonic tumorigenesis, thus illuminating its potential as a novel therapeutic target for inhibiting cancer growth." (PMID 32354028, 2020). "As a result, targeting KDM3A in patients with BCa can be a powerful strategy to overcome drug resistance and therefore cancer recurrence." (PMID 32354028, 2020). "KDM3 proteins, particularly KDM3A, can act as oncoproteins, making them potential therapeutic targets for cancer treatment." (PMID 32354028, 2020). "KDM3A transcriptome analysis revealed, in addition to Ets1 and MCAM, other genes previously implicated in the promotion of aggressive cancer properties, including the genes FYN, AXL, LOXL2 and PLAU." (PMID 32577157, 2020). "We also discuss existing KDM3A-related inhibitors and review their potential as therapeutic agents for overcoming cancer." (PMID 32354028, 2020). "Such consistency indicates that KDM3A overexpression starts in the early stage and remains high throughout cancer progression, suggesting that KDM3A is an essential contributor to cancer development, particularly even under normoxic conditions." (PMID 32354028, 2020). "Given the number of links of KDM3A to tumorigenesis and metastasis, KDM3A stands as an emerging promising therapeutic target in cancer treatment." (PMID 32354028, 2020). "Of the KDM3 proteins, KDM3A is especially deregulated or overexpressed in multiple cancers, making it a potential cancer therapeutic target." (PMID 32354028, 2020). "Using gene set enrichment analysis, it was identified that overexpressed KDM3A posttranscriptionally activates androgen signaling and cancer metabolic pathways, such as hypoxia and glycolytic pathways, thus upregulating oncogene expression." (PMID 32354028, 2020). "For the specific role of KDM3A in cancer, epigenomic and transcriptional cooperation with transcription factors is key." (PMID 29977600, 2018). "Transcriptional control of key players of cancer and AR signaling by KDM3A such as KLK3, NKX3-1, MYC were validated by chromatin immunoprecipitation coupled with quantitative real time polymerase chain reaction (ChIP-qRT-PCR)." (PMID 28416760, 2017). "For KDM3A to be an effective therapeutic target, depletion of KDM3A must affect cancer cell growth and/or cell survival." (PMID 25488809, 2015). "Our data support the observation that KDM3A is important for cancer cell proliferation and the dramatic cytostatic effect of KDM3A depletion on BCa cell growth demonstrates that KDM3A would be an attractive BCa therapeutic target." (PMID 25488809, 2015). "In cancer cells, KDM3A knockdown promotes cell cycle arrest, whereas elevated KDM3A levels promote G1/S transition." (PMID 24858415, 2014).